UBE2CP5 (ubiquitin conjugating enzyme E2 C pseudogene 5)
Gene: Transcribed processed pseudogene on chromosome 19 (57,867,970 to 57,868,834, forward strand). Ensembl gene ENSG00000270804.
Diseases named in the same sentence as UBE2CP5 in open-access papers:
UBE2CP5 is named in the same sentence as 1 disease in open-access papers, as found by Europe PMC text mining. Sharing a sentence is not in itself a finding about the gene and the disease.
UBE2CP5 shares sentences with these, for which no sentence is quoted: gastric cancer (1 paper).